PNMA8A (PNMA family member 8A)
Synonyms: PNMAL1; KIAA1183L; FLJ10781
Tractability: PROTAC: ubiquitination databases record sites on it.
Gene: Protein-coding gene on chromosome 19 (46,466,491 to 46,471,563, reverse strand). Ensembl gene ENSG00000182013.
Subcellular location (Human Protein Atlas): Nuclear bodies; Nucleoplasm; Cytosol
Gene Ontology:
Cellular component: nuclear body; nucleoplasm
Genetic constraint (gnomAD): Loss-of-function variants: 14 observed, 22.44 expected, observed/expected ratio (o/e) 0.62, 90% interval 0.41 to 0.98. The upper end of that interval is the gene's LOEUF score, 0.98, which puts it in group 4 of 6, group 1 being the genes least tolerant of losing a copy. Missense variants: 400 observed, 399.24 expected, observed/expected ratio (o/e) 1, 90% interval 0.92 to 1.09. Synonymous variants: 158 observed, 147.59 expected, observed/expected ratio (o/e) 1.07, 90% interval 0.94 to 1.22.
Homologues: Orthologues: macaque PNMA8A (95% identical), chimpanzee PNMA8A (84% identical), guinea pig PNMA8A (69% identical), rat Pnma8a (65% identical), rabbit PNMA8A (64% identical), mouse Pnma8a (62% identical). Paralogues in human: PNMA8B (25% identical), PNMA1 (23% identical), PNMA6E (22% identical), PNMA6A (22% identical), PNMA6F (22% identical), PNMA2 (21% identical), PNMA5 (20% identical), MOAP1 (19% identical), PNMA3 (19% identical), PNMA8C (17% identical), CCDC8 (10% identical), ZCCHC12 (9% identical), and 1 more.
Diseases named in the same sentence as PNMA8A in open-access papers:
PNMA8A is named in the same sentence as 6 diseases in open-access papers, as found by Europe PMC text mining. Sharing a sentence is not in itself a finding about the gene and the disease. The quoted sentences say what the papers report.
COVID-19 (1 paper, 2024). A disease caused by infection with severe acute respiratory syndrome coronavirus 2. "DAW1, ESF1, KCTD2, USP45, PNMA8A, SYNDIG1L, and CC2D2B are novel genes/proteins that may be linked to COVID-19." (PMID 38674024, 2024). "On the other hand, PNMA8A/PNMAL1 was also listed among stroke candidate genes, and ZNF385D and CPSF2, which are repressed by the S1 subunit, were also associated with inflammation and stroke in relevance to COVID-19." (PMID 38674024, 2024).
Stroke (1 paper, 2024). Sudden impairment of blood flow to a part of the brain due to occlusion or rupture of an artery to the brain. "Promoted PNMA8A/PNMAL1 was listed among stroke candidate genes, as well as among cytotoxicity-related genes in CD4+ and CD8+ T cells that mark progression to type 1 diabetes." (PMID 38674024, 2024). "Furthermore, PNMA8A/PNMAL1 was listed among the candidate genes for stroke, as well as among cytotoxicity-related genes in CD4+ and CD8+ T cells that mark progression to type 1 diabetes." (PMID 38674024, 2024).
cancer (2 papers, 2022 to 2024). A tumor composed of atypical neoplastic, often pleomorphic cells that invade other tissues. "XAF1, TRIM31, G0S2 and IFI6 have known roles in apoptosis or its prevention, while PAX7, TRIM31 and PNMA8A are involved in cell development/development of cancer." (PMID 38990812, 2024).
tumor (2 papers, 2022 to 2024). "Promoted PNMA8A/PNMAL1 is associated with paraneoplastic disorder, when the tumor immune response breaks immune tolerance and begins to attack the normal tissue." (PMID 38674024, 2024).
PNMA8A also shares sentences with these, for which no sentence is quoted: pancreatic ductal adenocarcinoma (1 paper); type 1 diabetes (1).